INS (insulin)
Diseases named in the same sentence as INS in open-access papers (continued):
Sharing a sentence is not in itself a finding about the gene and the disease.
Insulin resistance (continued). "Inflammation disrupts the effectiveness of insulin, and this insulin resistance and subsequent glucose and fat accumulation in the liver underpin the link between higher inflammation and obesity, as indexed by higher measures of adiposity (i.e., higher LAP)." (PMID 40285470, 2025). "This chronic low-grade inflammation can interfere with the insulin signaling pathway, ultimately leading to insulin resistance." (PMID 40563287, 2025). "The decrease in glucose uptake and cellular responses to insulin is a known characteristic of insulin resistance." (PMID 39873298, 2025). "The study concluded that anthocyanins (pelargonidin) in strawberries reduced the post-prandial insulin demand to manage post-prandial glucose in obese individuals with insulin resistance." (PMID 39136514, 2025). "Insulin resistance is a pathological condition wherein cells exhibit a reduced responsiveness to insulin, resulting in impaired glucose uptake and elevated blood glucose levels." (PMID 40688596, 2025). "Ceramides are central mediators in the development of insulin resistance, acting through multiple molecular pathways to disrupt insulin signaling, promote inflammation, and alter lipid metabolism." (PMID 40422918, 2025). "Multi-scale DTs for adiposity-driven insulin resistance successfully integrate mechanistic models of glucose metabolism, body composition, and cellular insulin signaling to predict responses to dietary and pharmacological interventions." (PMID 41341463, 2025). "Vitexin and isovitexin flavonoids not only affected the absorption of peripheral glucose in insulin and non-insulin sensitive tissues but also showed the potential to restore insulin resistance in HepG2 cells by enhancing cellular uptake of glucose." (PMID 40725244, 2025). "A multi-scale DT for adiposity-driven insulin resistance integrates mechanistic models of glucose metabolism, body composition, and cellular insulin signaling." (PMID 41341463, 2025). "Insulin resistance (IR) is characterized by weakened physiological function of insulin, wherein normal insulin levels fail to elicit an adequate physiological response." (PMID 40144296, 2025). "Lipid accumulation in the liver reduces insulin efficiency and eventually leads to insulin resistance." (PMID 40560451, 2025). "Animals in the diabetic control (DC) showed severe insulin resistance manifested by elevations in the fasting serum insulin levels." (PMID 39803222, 2025). "In clinical trials, curcumin as an effective antihyperglycaemic agent, has been found to improve insulin resistance and reduce insulin and blood glucose levels." (PMID 40538540, 2025). "Insulin resistance is defined as impaired insulin-mediated effects in several organs, including impaired glucose uptake in skeletal muscle, impaired suppression of glucose production in the liver, and impaired suppression of lipolysis in adipose tissue." (PMID 39928502, 2025). "It was found that the expression of NF-κB and JNK following the consumption of a high-fat diet disturbed insulin signaling proteins in the cells, resulting in insulin resistance." (PMID 40076566, 2025). "Patients with PCOS often have disruptions in the insulin signaling pathway, which can manifest clinically as hyperinsulinemia and insulin resistance." (PMID 41141267, 2025). "The bolus insulin units were reduced with DPP-4 compared to placebo and the basal insulin doses were the same between the two groups suggesting possible improvement in insulin resistance." (PMID 41026724, 2025). "Insulin resistance (IR) develops in the skeletal muscle, liver, and adipose tissues responsive to insulin before T2D onset." (PMID 40729355, 2025). "Although insulin levels were similar in all groups, insulin resistance was significantly reduced in the Stevia group." (PMID 40087612, 2025). "Overall, these results suggest that TSFE minimizes inflammation-induced insulin resistance and improves insulin sensitivity in mature adipocytes." (PMID 40807540, 2025).
Insulin resistance (continued). "Key immunometabolic indices, notably Frailty Index (FRAILTY) and fasting serum insulin (FSI), were significantly associated with increased DR risk, whereas the metabolic score for insulin resistance (METS) showed a protective effect." (PMID 40778361, 2025). "The heterogeneity of double diabetes results from genetic variants that affect insulin resistance and autoimmune responses through HLA, TCF7L2, PTPN22, and INS genes." (PMID 40225541, 2025). "Our results show that Tac activates systemic RAS and blockage of RAS by Val alleviates Tac-induced insufficient insulin and insulin resistance." (PMID 40495121, 2025). "Insulin resistance is characterized by reduced sensitivity of the body to insulin, which leads to a decrease in the effectiveness of insulin in facilitating glucose uptake and utilization, thereby resulting in elevated blood sugar levels." (PMID 40453655, 2025). "This increases insulin sensitivity in adipose tissue, muscle, and liver by promoting glucose uptake and reducing insulin resistance." (PMID 40771585, 2025). "Metabolic parameters, including fasting plasma glucose, insulin levels, hemoglobin A1c (HbA1c), and the insulin resistance index, homeostatic model assessment for insulin resistance (HOMA-IR), were significantly higher in individuals with obesity." (PMID 40548377, 2025). "Lower HOMA-IR values reflect lower blood glucose levels in relation to circulating insulin, indicating enhanced insulin sensitivity, whereas higher values suggest increased insulin resistance." (PMID 41367198, 2025). "Nevertheless, few investigations have systematically explored how sociodemographic factors, healthy behaviors, and QoL jointly influence insulin resistance as measured by validated non-insulin-based indices." (PMID 40843744, 2025). "Elevated hs-CRP impairs the insulin signaling pathway that promotes glucose translocation by phosphorylating the insulin receptor substrate-1, thereby promoting insulin resistance." (PMID 39940942, 2025). "Accordingly, a recent study has highlighted the role of n-3 PUFAs in improving mitochondrial biogenesis and function, particularly in insulin-sensitive tissues, resulting in better glucose utilization and reduced insulin resistance." (PMID 40219010, 2025). "As obesity and insulin resistance progress, insulin demand increases and β-cell function declines, leading to reduced insulin supply and rising blood glucose levels." (PMID 40666490, 2025). "Studies have shown that O-GlcNAcylation of PDK1 and AKT impairs the insulin signaling pathway, further contributing to insulin resistance." (PMID 41373704, 2025). "In the early stages of T2DM, there are multiple types of immune cells infiltrating in insulin-sensitive tissues, where they disrupt tissue homeostasis, exacerbate insulin resistance, and perpetuate systemic inflammation." (PMID 41357227, 2025). "Type 1 diabetes and type 2 diabetes are common metabolic disorders attributed to inadequate insulin secretion and insulin resistance, respectively." (PMID 40735430, 2025). "Further, DAG accumulation contributes to insulin resistance in skeletal muscle by inhibiting the insulin signalling pathway through protein kinase C (PKC) activation; however, isoforms of PKC involved vary depending on the experimental settings." (PMID 40641114, 2025). "MSC therapy significantly reduces fasting and postprandial blood glucose, HbA1c, and insulin requirements while improving C‐peptide levels and insulin resistance with mild and manageable symptoms like fever, nausea, headache, and minor hypoglycemia." (PMID 40290901, 2025). "Their excessive secretion can impair the body’s insulin signaling pathway, thereby exacerbating insulin resistance and elevating blood glucose levels." (PMID 40260393, 2025).
Insulin resistance (continued). "Acromegaly patients had significantly higher fasting glucose and fasting insulin levels compared to controls, and the homeostasis model assessment of the insulin resistance (HOMA-IR) index was significantly lower in the study group than in the controls." (PMID 40149642, 2025). "β‐cell function (i.e., the capacity to secrete insulin) plays a crucial role in the development of T2D, as failure to compensate for an increased demand for insulin owing to insulin resistance is central to the pathogenesis of the disease." (PMID 40898610, 2025). "Subsequently, the HOMA index was calculated to assess the insulin resistance, insulin sensitivity, and β-cell function." (PMID 40863931, 2025). "Compounds such as quercetin, apigenin, and chrysoeriol, which have the potential to improve insulin resistance, enhance insulin secretion and reduce blood glucose levels." (PMID 40684140, 2025). "Adipose tissue inflammation also promotes insulin resistance and hyperinsulinemia, with insulin and insulin-like growth factors exerting mitogenic and anti-apoptotic effects." (PMID 41299673, 2025). "The treatment did not increase hypoglycemia risk, while adverse events included diabetic ketoacidosis mainly related to a reduction in insulin dose or illness and insulin resistance." (PMID 39998445, 2025). "In hypothyroidism, reduced THR activity impairs glucose production and insulin sensitivity, contributing to hyperglycemia and insulin resistance." (PMID 40926269, 2025). "In CRC, for example, hypoxia-induced inflammation and altered insulin signaling pathways lead to increased insulin resistance and hyperinsulinemia, which can promote colorectal carcinogenesis through the insulin/IGF axis." (PMID 40722646, 2025). "Adiponectin, a specific protein secreted by adipocytes, binds to G protein-coupled receptors and plays pivotal role in enhancing insulin sensitivity, regulating carbohydrate and lipid metabolism, and correcting hyperinsulinemia and insulin resistance." (PMID 41048434, 2025). "Preclinical data have demonstrated that resveratrol can be utilized in diabetes management through correction of insulin signaling defects, improvement in insulin resistance, and prevention of pancreatic beta cells’ dysfunction." (PMID 40943191, 2025). "This difference in response underscores the intricate nature of insulin’s metabolic control, particularly in insulin resistance." (PMID 40725728, 2025). "Insulin resistance in the background of PCOS partially depends on increased serine phosphorylation of an insulin receptor that influences insulin signaling pathways." (PMID 39866289, 2025). "Insulin resistance (IR) refers to a physiological condition in which peripheral tissues, such as skeletal muscle, liver, and adipose tissues, are insensitive to insulin action, leading to impaired glucose utilization and type 2 diabetes mellitus (T2DM)." (PMID 40070461, 2025). "Tubbs and colleagues demonstrated in OB/OB mice and diet-induced insulin resistance mouse models that the integrity of MAMs is essential for insulin signaling." (PMID 39966707, 2025). "Insulin resistance is a pathophysiological condition which necessitates a higher level of insulin secretion for the maintenance of circulating glucose levels in the normal range." (PMID 41328998, 2025). "Experimental studies on insulin-resistant 3T3-L1 adipocytes from mice provided evidence that mitochondrial oxidative stress is the origin of insulin resistance, while oxidative phosphorylation remained unaffected." (PMID 41514592, 2025). "The non-insulin-based IR indicators, such as triglyceride-glucose index, metabolic score for insulin resistance, and estimated glucose disposal rate, were independently associated with the frailty progression and physical function decline." (PMID 40559405, 2025). "CSH-1 has insulin-antagonistic effects and contributes to maternal insulin resistance, ensuring increased glucose availability for the fetus, thereby regulating fetal growth." (PMID 41373661, 2025).
Insulin resistance (continued). "Metabolic conditions modify associations between insulin resistance and brain glucose metabolism; ie, most individuals with insulin resistance display hypometabolism during fasting and hypermetabolism during insulin stimulation." (PMID 39185744, 2025). "On the other hand, dasatinib has shown potential benefits in T2DM patients by reducing insulin resistance and improving glycemic control, potentially facilitating insulin production and decreasing insulin requirements." (PMID 40292250, 2025). "In adipose tissue, diminished PGC-1α levels and impaired insulin signaling molecules correlate with metabolic dysfunction, further aggravating systemic insulin resistance in affected subjects." (PMID 40918255, 2025). "Through CB1 activation, AEA and 2-AG stimulate lipogenesis, reduce adiponectin release, modulate insulin secretion, and influence hepatic gluconeogenesis, thereby linking caloric excess to weight gain and insulin resistance." (PMID 40806101, 2025). "Remarkably, this intervention led to a normalization of blood glucose concentration, reduction of glucose intolerance and insulin resistance, and an increase in serum insulin levels when compared to the T2D and T2D/IgG groups." (PMID 39808380, 2025). "TNF-α is a key cytokine released from adipocytes and is known to dysregulate leptin and inhibit glucose-stimulated insulin secretion leading to insulin resistance." (PMID 41463113, 2025). "In the first case, MASLD stems from visceral adiposity leading to hepatic insulin resistance, which impairs the ability of insulin to inhibit hepatic glucose and VLDL production." (PMID 40244110, 2025). "Normal islet histology after HFD treatment is consistent with the start of the development of insulin resistance as the beta-cells first appear normal but later have impaired function as measured by elevated insulin secretion and HOMA-B." (PMID 40732915, 2025). "The highest β cell activity (% β) and insulin sensitivity (% S) in D (Thiamine & Niacin) confirm the most advantageous effect of the vitamin combination on glycemia, insulin resistance, and dyslipidemia." (PMID 39877627, 2025). "Once insulin resistance develops, the body’s sensitivity and responsiveness to the physiological effects of insulin are reduced." (PMID 40589515, 2025). "In particular, SIRT1 overexpression seems to improve insulin sensitivity and to reduce insulin resistance, while its downregulation inhibits insulin signalling and glucose transport into adipocytes." (PMID 39976627, 2025). "Serum insulin, acting through IR, directly enhanced cytotoxic NK activity toward HSCs, alleviating fibrosis in early hyper-insulinemic stages of insulin resistance." (PMID 40643462, 2025). "Insulin resistance diminishes the sensitivity of adipose tissue to insulin, resulting in an increased release of free fatty acids (FFAs) from adipocytes and augmented TG synthesis within the liver." (PMID 40996074, 2025). "This decrease in GLUT-4 expression impairs the ability of insulin to facilitate glucose entry into adipocytes, contributing to the overall insulin resistance observed in women with PCOS." (PMID 40066975, 2025). "Research shows that a sedentary lifestyle contributes to insulin resistance and high levels of circulating insulin and insulin-like growth factors, both of which correlate with an increased breast cancer risk." (PMID 40989682, 2025). "This sustained inflammatory response, triggered by metabolic signals, can impede insulin function, disrupt metabolic equilibrium, and represents a pivotal link between obesity and related conditions such as insulin resistance and type 2 diabetes." (PMID 40519917, 2025). "Cer inhibit Akt phosphorylation in pancreatic β-cells, disrupting insulin signaling and acting synergistically with mitochondrial DNA damage to exacerbate insulin resistance." (PMID 40980166, 2025).
Insulin resistance (continued). "Both groups were similar regarding fasting blood glucose, fasting insulin, Homeostasis Model Assessment of Insulin Resistance (HOMA-IR), and hemoglobin A1c (HbA1c) ­levels (p>0.05 for all)." (PMID 40531768, 2025). "At the ovarian level, GCs from both lean and overweight/obese women with PCOS have been shown to display a selective insulin resistance, characterized by impaired metabolic responses while preserving insulin-stimulated steroidogenesis and mitotic activity." (PMID 40723795, 2025). "Insulin resistance, islet β-cell dysfunction, and a relative shortage in insulin production are critical pathophysiological mechanisms in the occurrence and progression of GDM." (PMID 41272565, 2025). "Insulin resistance consists of an insulin action defect in insulin-sensitive tissues in charge of glucose storage, such as adipose tissues, the liver, and muscles." (PMID 40943107, 2025). "This creates a vicious cycle: Inflamed adipose tissue secretes less adiponectin (an insulin-sensitizing hormone) and more resistin and proinflammatory cytokines, thereby exacerbating systemic insulin resistance." (PMID 40871736, 2025). "Previously developed models described the dynamics of glucose, insulin, and free fatty acids in plasma, the effects of caloric restriction on insulin resistance, or the impacts of isocaloric diets with varying macronutrient ratios." (PMID 41465237, 2025). "Emodin improved insulin sensitivity and alleviated insulin resistance by increasing hepatic glucose utilization and muscle and fat glucose uptake through the IRS/PI3K/Akt/forkhead box O 1 (FoxOl) pathway." (PMID 39942768, 2025). "Insulin resistance remained unaltered; however, %S and %B improved markedly, reflecting elevated serum insulin levels." (PMID 41227734, 2025). "One of the key mechanisms involves the inhibition of glucose transporter type 4 (GLUT-4) translocation by ceramides, which impairs glucose uptake in insulin-sensitive tissues, thus leading to insulin resistance." (PMID 40700071, 2025). "Improving insulin resistance in peripheral tissue and liver would increase insulin sensitivity and thus is another target for preventing and treating hyperglycemia." (PMID 39136514, 2025). "Some researchers conclude that steroids stimulate hepatic glucose production and lipolysis in adipose tissue, leading to increased insulin resistance and impairment of insulin secretion from β-cells in the pancreas." (PMID 41567924, 2025). "Previous research has indicated that LV-HIIT enhances mitochondrial enzyme activity, thereby improving insulin resistance, and promotes glycogen depletion and subsequent resynthesis, which contributes to improved post-exercise insulin sensitivity." (PMID 41488923, 2025). "Insulin injections are effective in temporarily alleviating symptoms, and oral hypoglycemic agents (OHAs) have been reported to transiently improve insulin resistance and enhance insulin production." (PMID 39851765, 2025). "Primary outcomes included fasting insulin (FI), Glycosylated Hemoglobin (HbA1c), and insulin resistance (HOMA-IR)." (PMID 41370222, 2025). "Among the blood laboratory results, glucose, insulin, homeostatic model assessment of insulin resistance (HOMA-IR), high-density lipoprotein, total bilirubin, and leptin levels were significantly associated with the total PANSS score." (PMID 40048458, 2025). "The authors also used the fasting insulin level as an exposure factor, which provides a proxy for the degree of insulin resistance." (PMID 40669383, 2025). "In vivo, these AdEVs improved insulin secretion and glucose tolerance, highlighting their role in β-cell adaptation to insulin resistance and suggesting their therapeutic potential for improving glucose tolerance." (PMID 40001534, 2025). "Impaired insulin secretion and insulin resistance are recognized as pivotal factors in the pathogenesis of T2DM." (PMID 40078932, 2025).